ST14 (ST14 transmembrane serine protease matriptase)
Diseases named in the same sentence as ST14 in open-access papers (continued):
Sharing a sentence is not in itself a finding about the gene and the disease.
cancer (22 papers, 2005 to 2025). A tumor composed of atypical neoplastic, often pleomorphic cells that invade other tissues. "There are multiple genetically modified mouse models that exhibit phenotypes of Prss14/ST14 associated cancer." (PMID 31426843, 2019). "Matriptase, a type II transmembrane serine protease encoded by the suppressor of tumorigenicity-14 (ST-14) gene, can be found in all types of epithelial tissues including normal tissue and epithelial derived cancer cells." (PMID 26488575, 2015). "This study focuses on the oncogene ST14, encoding the type II transmembrane protease Matriptase-1 that upon hyperactivation—as for instance due to genetic loss of its cognate transmembrane inhibitor Hai1—can drive different carcinomas." (PMID 37566613, 2023). "If antibody mediated endocytosis is sufficient, these reagents can also be good lead materials as antibody drug conjugates for targeting the removal of early cancer cells with unactivated Prss14/ST14 protease on the surface." (PMID 31426843, 2019). "The cellular functions of Prss14/ST14 for cancer progression and metastasis have been studied extensively using Prss14/ST14 high expressing cells and mouse models." (PMID 31426843, 2019). "Epi-SP caused a statistically significant reduction in the numbers of metastasis nodules, indicating that immunizing cancer self Prss14/ST14 antigens can interfere with cancer metastasis." (PMID 31426843, 2019). "Multiple pathologic analyses of cancer patients’ samples showed that over-expression of Prss14/ST14 is consistently found in progressed cancers of epithelial types." (PMID 31426843, 2019). "Among pericellular proteases, human matriptase (also named as MT-SP1, TADG-15, ST14) receives much attention because of its role in tumorigenesis and cancer progression." (PMID 29118397, 2017). "In any case, detail mode of action studies on the mechanism of ST14/Prss14 expression in different cell populations, cancer tissues, and the microenvironment will be necessary to target ST14/Prss14 with therapeutic approaches." (PMID 27167193, 2016). "We interpret these as supporting results that the majority of the ST14/Prss14 message is coming from the ER− cancer tissue." (PMID 27167193, 2016). "Because the increased ratio of ST14/Prss14 to its inhibitor SPINT1 was observed in some carcinomas, we examined the ratio of ST14/Prss14 to SPINT1 and SPINT2." (PMID 27167193, 2016). "Whereas the macrophage-depleted stromal fraction showed high expression of TF, PAR1, PAR2, and matriptase (ST14), a known cancer cell-expressed serine protease, EPCR was expressed at similar levels by macrophages and other cells in the tumor microenvironment." (PMID 23593394, 2013). "A new specific monoclonal antibody mAb3F3 generated against the engineered loop structure could reduce cell migration, eliminate metastasis in PyMT mice, and can detect the Prss14/ST14 protein expressed in various human cancer cells." (PMID 31426843, 2019). "Furthermore, the expression of ST14 has been demonstrated to be up-regulated in various human cancer histotypes such as breast, cervix, ovaries, prostate, esophagus and liver cancers." (PMID 31519199, 2019). "To exclude the possibility that the increased expression level of ST14/Prss14 in ER− patients may have resulted from other types of cells in the cancer microenvironment, we analyzed stromal or immune signature genes." (PMID 27167193, 2016). "Therefore, ST14/Prss14 expression can be also contributed from a cancer microenvironment." (PMID 27167193, 2016). "The HT29 line-derived EV proteins ST14, and KIF23 were annotated against the KEGG database as belonging to the signaling pathway “MicroRNAs in cancer”." (PMID 32916986, 2020). "The functional linkage between ST14 and SPINT1 has important implications for the development of cancer." (PMID 31519199, 2019).
cancer (continued). "These include a number of known or potential tumour suppressor genes (BCSC-1, CHEK1, ST14, ATM, P53AIP1), genes with proposed roles in cancer progression (BARX2), apoptosis (PIG8, P53AIP1) and oncogenesis (FLI1, ETS1), and a DNA damage-inducible gene (DDI1)." (PMID 18506147, 2008). "In human epidermal tumors, ST14 can induce activation of the PI3K-Akt signaling pathway, and it can also cooperate with Ras-dependent signaling and independent signaling pathways to drive cancer." (PMID 38468232, 2024). "To date, differential expression of ST14 according to different methylation patterns has not been investigated yet; and there were few studies addressing the role of ST14 methylation in cancer." (PMID 34418985, 2021). "This apparent contradiction is not likely due to ST14/Prss14 expression in a cancer microenvironment, nor due to negative regulation by ER." (PMID 27167193, 2016). "In addition, a study involving IHC shows ST14/Prss14 expression in cancer tissue, not in stromal tissue." (PMID 27167193, 2016). "The ratio of ST14/Prss14 to SPINT1, ratio(I), and that of ST14/Prss14 to SPINT2, ratio(II), showed no big difference among the cancer stages." (PMID 27167193, 2016).
tumor (22 papers, 2005 to 2025). "The Angiopoietin 2 (ANG2), having a role in hepatocyte proliferation, and the ST14 Transmembrane Serine Protease Matriptase (ST14), whose inhibition was associated with tumour cell invasion and metastasis, were also down-regulated." (PMID 38528259, 2024). "By using multi-transgenic crosses to manipulate expression of ST14/Prss14 and its inhibitor SPINT2, Thomas Bugge's group showed that ST14/Prss14 can initiate tumorigenesis by causing tumor-associated inflammation." (PMID 27167193, 2016). "The SPSS genes are all expressed in the LUAD tumor samples, while in the BL samples ST14 is expressed at a detectable level in some cases (in the red color), but without much prostasin or HAI co-expression (in the blue color)." (PMID 39996720, 2025). "Reduced expression of ST14 slowed tumor growth in mice by impairing the pro-HGF/c-Met signaling pathway and cell proliferation." (PMID 38339272, 2024). "Expression levels varied for the serine proteases with an increase in tumor mRNA levels for HPN and HGFA, while ST14 was downregulated in tumor samples." (PMID 38212428, 2024). "By contrast, within tumor samples, DMPs with higher methylation in the gene body were found to be linked to a high GAM status, which was in turn associated with a low ST14 expression level." (PMID 34418985, 2021). "Many known specific substrates for Prss14/ST14 protease are well known for their roles in tumor progression and metastasis and can be categorized into multiple families." (PMID 31426843, 2019). "This study also showed that Prss14/ST14 plays a critical role in cMet signaling in response to HGF secreted from the fibroblast in the tumor microenvironment." (PMID 31426843, 2019). "Similarly, in the present study, hypermethylation in the gene body region was correlated with a higher ST14 gene expression level in tumor tissues compared with that in normal tissues in the TCGA BRCA cohort." (PMID 34418985, 2021). "Since Prss14/ST14 plays the critical role of activating multiple downstream substrates, we made an assumption that inhibiting function with antibodies can block tumor metastasis and increase survival of tumor patients." (PMID 31426843, 2019). "Prss14/ST14 knockdown cells were used to test function in tumor growth and metastasis, peptides derived from the autocatalytic loop for activation were tested as preventive metastasis vaccine, and monoclonal and humanized antibodies to the same epitope were tested as new therapeutic candidates." (PMID 31426843, 2019). "When the K5 promoter is used in transgenic expression of Prss14/ST14, mice spontaneously develop skin adenoma that can be accelerated by tumor promoting chemicals." (PMID 31426843, 2019). "Prss14/ST14 knock down cells (EpiKD) and their control partner cells (Con) were orthotopically injected into mammary fat pads, and followed by the analysis of survival, tumor onset, growth of the primary tumor, and metastasis to the lung." (PMID 31426843, 2019).
infection (2 papers, 2023). The state of being infected such as from the introduction of a foreign agent such as serum, vaccine, antigenic substance or organism. "We suggest a viral-induced coagulation mechanism, in which prothrombin is activated by infection-induced transmembrane serine proteases, such as ST14 and TMPRSS11D, on NHBE cells." (PMID 37821447, 2023). "Interestingly, ST14 displayed a sporadic infection pattern in all three age categories." (PMID 37264466, 2023).
benign tumors (1 paper, 2024). "In addition, the ST14 positive expression rates in borderline ovarian tumors and benign tumors were 83.3% (10/12) and 76.9% (10/13), which were significantly higher than those in normal ovarian epithelial tissues (P = 0.002, 0.007)." (PMID 38468232, 2024).
genodermatosis (1 paper, 2017). "Thus, the identified equine ST14:c.388G>T variant is an excellent candidate causative variant for NFS, and the affected horses represent a large animal model for a known human genodermatosis." (PMID 28235824, 2017).
vasculopathy (1 paper, 2009). "Given the known substrates of this protease, ST14 induction during vasculopathy and in AF of fetuses with CHDs may affect differentiation, adhesion/migration and growth." (PMID 19156209, 2009).
ST14 also shares sentences with these, for which no sentence is quoted: glioma (2 papers); hypohidrosis (2); hypotrichosis (2); acute myeloid leukemia (1); age-related macular degeneration (1); atherosclerosis (1); autosomal recessive congenital ichthyosis (1); breast invasive carcinoma (1); Burkitt lymphoma (1); childhood asthma (1); cholangiocarcinoma (1); clear cell adenocarcinoma (1); clear cell adenocarcinoma of the ovary (1); connective tissue disorder (1); Crohn disease (1); dysplasia (1); endometrioid adenocarcinoma (1); esophageal adenocarcinoma (1); Fraser syndrome (1); gastric adenocarcinoma (1); heart malformations (1); Hyperglycemia (1); influenza (1); kidney cancer (1); lung adenocarcinoma (1); lymphoid neoplasm (1); melanoma (1); non-small cell lung carcinoma (1); osteogenesis imperfecta (1); other (1).
A further 7 diseases each share a sentence with ST14 in 1 paper.